DERL1 (derlin 1)
Description:
Functional component of endoplasmic reticulum-associated degradation (ERAD) for misfolded lumenal proteins. Forms homotetramers which encircle a large channel traversing the endoplasmic reticulum (ER) membrane. This allows the retrotranslocation of misfolded proteins from the ER into the cytosol where they are ubiquitinated and degraded by the proteasome. The channel has a lateral gate within the membrane which provides direct access to membrane proteins with no need to reenter the ER lumen first. May mediate the interaction between VCP and the misfolded protein. Also involved in endoplasmic reticulum stress-induced pre-emptive quality control, a mechanism that selectively attenuates the translocation of newly synthesized proteins into the endoplasmic reticulum and reroutes them to the cytosol for proteasomal degradation. By controlling the steady-state expression of the IGF1R receptor, indirectly regulates the insulin-like growth factor receptor signaling pathway. (Microbial infection) In case of infection by cytomegaloviruses, it plays a central role in the export from the ER and subsequent degradation of MHC class I heavy chains via its interaction with US11 viral protein, which recognizes and associates with MHC class I heavy chains. Also participates in the degradation process of misfolded cytomegalovirus US2 protein.
Synonyms: DER1; MGC3067; PRO2577; FLJ13784; DER-1; derlin-1
Tractability: Small molecule: a structure with a bound ligand is known. Antibody: UniProt predicts a signal peptide or a membrane-spanning region. PROTAC: its protein half-life has been measured.
Gene: Protein-coding gene on chromosome 8 (123,013,170 to 123,042,406, reverse strand). Ensembl gene ENSG00000136986.
Subcellular location: Endoplasmic reticulum membrane
Subcellular location (Human Protein Atlas): Endoplasmic reticulum
Pathways (Reactome):
Metabolism of proteins: E3 ubiquitin ligases ubiquitinate target proteins; N-glycan trimming in the ER and Calnexin/Calreticulin cycle
Disease: Defective CFTR causes cystic fibrosis
Immune System: AMPK-induced ERAD and lysosome mediated degradation of PD-L1(CD274)
Transport of small molecules: ABC-family protein mediated transport
Gene Ontology:
Molecular function: ATPase binding; identical protein binding; MHC class I protein binding; protease binding; protein binding; protein-containing complex binding; signal recognition particle binding; ubiquitin protein ligase binding; ubiquitin-specific protease binding; signaling receptor activity
Biological process: cellular response to misfolded protein; endoplasmic reticulum unfolded protein response; ERAD pathway; positive regulation of protein ubiquitination; protein destabilization; response to unfolded protein; retrograde protein transport, ER to cytosol; establishment of protein localization; ubiquitin-dependent protein catabolic process; cellular response to stress; proteasomal protein catabolic process; proteasome-mediated ubiquitin-dependent protein catabolic process
Cellular component: ATPase complex; Derlin-1 retrotranslocation complex; Derlin-1-VIMP complex; endoplasmic reticulum; endoplasmic reticulum membrane; membrane; cytoplasm; early endosome; endoplasmic reticulum quality control compartment; late endosome
Genetic constraint (gnomAD): Loss-of-function variants: 18 observed, 36.24 expected, observed/expected ratio (o/e) 0.5, 90% interval 0.34 to 0.74. The upper end of that interval is the gene's LOEUF score, 0.74, which puts it in group 3 of 6, group 1 being the genes least tolerant of losing a copy. Missense variants: 241 observed, 301.03 expected, observed/expected ratio (o/e) 0.8, 90% interval 0.72 to 0.89. Synonymous variants: 110 observed, 108.11 expected, observed/expected ratio (o/e) 1.02, 90% interval 0.87 to 1.19.
Homologues: Orthologues: chimpanzee DERL1 (100% identical), pig DERL1 (99% identical), rabbit DERL1 (99% identical), guinea pig DERL1 (98% identical), mouse Derl1 (98% identical), rat Derl1 (93% identical), zebrafish derl1 (86% identical), tropical clawed frog derl1 (85% identical), dog DERL1 (61% identical), macaque DERL1 (58% identical), Caenorhabditis elegans cup-2 (47% identical), Drosophila melanogaster Der-1 (41% identical). Paralogues in human: DERL2 (33% identical), DERL3 (31% identical).
Diseases named in the same sentence as DERL1 in open-access papers:
DERL1 is named in the same sentence as 63 diseases in open-access papers, as found by Europe PMC text mining. Sharing a sentence is not in itself a finding about the gene and the disease. The quoted sentences say what the papers report.
breast carcinoma (18 papers, 2008 to 2025). "In breast cancer, miR-30b can directly target Derlin-1 for negative regulation, and the loss of Derlin-1 inhibits the phosphorylation of AKT." (PMID 35291564, 2022). "Similarly, higher DERL1 expression in lung adenocarcinoma and breast cancer patients is associated with poor prognosis as well." (PMID 39040102, 2024). "Although lymph node metastasis is an indicator of poor prognosis of patients with breast carcinomas, a long-term follow-up is warranted to clarify whether derlin-1 expression is associated with the outcome in breast cancer, especially in lymph node-negative breast cancer." (PMID 18205950, 2008). "Positive Derlin-1 expression has been detected in 66.7% and 70% of the breast carcinoma tissues and colon cancer tissues, respectively." (PMID 35205628, 2022). "In human breast cancer, Derlin-1 was reported to protect cancer cells by eliminating ER stress-induced apoptosis and further contribute to the metastatic properties in cancer cells." (PMID 35205628, 2022). "Previous reports have shown that DERL1 is overexpressed in breast cancers and protects cancer cells from ER stress-induced apoptosis." (PMID 33946525, 2021). "Derlin-1 was has been reported to induce proliferation and invasion in a variety of cancers including lung and breast cancers." (PMID 28178653, 2017). "Derlin-1 expression is elevated in breast cancer and relieves ER stress-induced apoptosis in breast cancer cells." (PMID 28903408, 2017). "Derlin-1 expression is elevated in breast cancer and correlates with tumor grade and lymph node metastasis." (PMID 28178653, 2017). "Derlin-1 knockdown was also reported to sensitise breast cancer cells to ER stress-induced apoptosis." (PMID 24944523, 2014). "Data in breast cancer cells show that DERL1 expression is increased by ER stress while DERL1 knockdown resulted in decreased development of cancer cells." (PMID 24489661, 2014). "Recent studies reported that Derlin-1 is overexpressed in carcinomas, such as lung cancer, breast cancer and colon cancer." (PMID 24944523, 2014). "Surgical specimens of human breast cancer and/or paired normal tissues from the same patients were collected for immunohistochemical and/or Western blot analysis with anti-human derlin-1 antibody." (PMID 18205950, 2008). "A synthetic small interfering RNA against derlin-1 was introduced into breast cancer cells to inhibit derlin-1 expression." (PMID 18205950, 2008). "On examining the expression of derlin-1 in human breast cancer cell lines, we found that derlin-1 expression was enhanced by ER stress-inducing agents." (PMID 18205950, 2008). "Furthermore, this study demonstrated that derlin-1 knockdown in breast cancer cells rendered cancer cells more susceptible to ER stress-induced apoptosis, indicating that derlin-1 overexpression in breast cancer may enhance cancer cell survival following exposure to stress." (PMID 18205950, 2008). "The expression of derlin-1 in human breast cancer cell lines was detected by reverse transcription-polymerase chain reaction or Western blot." (PMID 18205950, 2008). "The expression of derlin-1 in human breast carcinoma correlated with tumor grade and axillary lymph node metastasis." (PMID 18205950, 2008). "Of the breast carcinomas, 28 of 42 (66.7%) expressed moderate to high levels of derlin-1, whereas derlin-1 rarely expressed in normal mammary epithelial cells." (PMID 18205950, 2008). "These analyses demonstrated that 66.7% of the breast carcinoma tissues expressed derlin-1, whereas derlin-1 was rarely expressed in normal mammary glands." (PMID 18205950, 2008). "In addition to its role in breast cancer, Derlin‐1 is overexpressed in muscle invasive bladder cancer, where its elevated expression correlates with poor prognosis." (PMID 41015904, 2025).
breast carcinoma (continued). "An elevated expression level of Derlin-1 may correlate with the malignant behavior of several cancer types, including liver cancer, breast cancer, lung cancer, head and neck cancer, and colon cancer." (PMID 35205628, 2022). "Derlin-1 can relieve ER stress-induced apoptosis in breast cancer cells." (PMID 28178653, 2017). "Overexpression of Derlin-1 induced cell apoptosis by attenuating ER stress in breast cancer." (PMID 27977784, 2016). "A previous study showed that expression of Derlin-1 increases in human breast carcinoma and protects cancer cells from apoptosis induced by ER stress, suggesting that it may confer metastatic properties to cancer cells." (PMID 27977784, 2016). "The level of Derlin-1 expression in higher-grade breast cancers has been demonstrated to be greater than that in lower-grade tumors, which suggests that Derlin-1 expression may be associated with a more malignant phenotype." (PMID 27977784, 2016). "Similarly, recent data in breast cancer cells showed that DERL1 expression is increased by ER stress while DERL1 knockdown resulted in decreased development of cancer cells." (PMID 20682045, 2010). "Derlin-1 knockdown sensitized breast cancer cells to ER stress-induced apoptosis." (PMID 18205950, 2008). "Since derlin-1 is frequently overexpressed in breast tumors, we investigated whether derlin-1 was constitutively overexpressed or induced by stress inducers in breast cancer cell lines." (PMID 18205950, 2008). "Derlin-1 expression significantly correlated with axillary lymph node metastasis of breast cancer." (PMID 18205950, 2008). "Notably, Derlin-1 can relieve ER stress-induced apoptosis in breast cancer cells." (PMID 24944523, 2014). "Notably, derlin-1 expression was more strongly present in higher-grade breast carcinomas than in lower-grade tumors, suggesting that derlin-1 expression may correlate with a more malignant phenotype." (PMID 18205950, 2008). "The observed derlin-1 overexpression in breast cancer, together with its function in relieving ER stress-induced apoptosis, suggests that regulation of the ER stress response pathway may be critical in the development and progression of breast cancer." (PMID 18205950, 2008). "Thus, derlin-1 expression may protect breast cancer cells against ER stress-induced apoptosis." (PMID 18205950, 2008). "In view of this, our data relate to previous findings by demonstrating that derlin-1, one part of the ERAD machinery and an effecter downstream of XBP-1, is frequently overexpressed in breast cancer." (PMID 18205950, 2008). "Whereas a high level of derlin-1 was detected in SKBR-3 cells, derlin-1 expresses at a low level in other non-treated breast cancer cell lines." (PMID 18205950, 2008). "In summary, this study demonstrated that derlin-1 expression is not constitutively overexpressed in some breast cancer cell lines but can be significantly induced by serum starvation and agents that disturb ER function." (PMID 18205950, 2008). "Because the roles of derlin-1 in human cancer have not yet been characterized, we investigated the expression of derlin-1 in human breast carcinoma and whether it protected cancer cells against ER stress-induced apoptosis." (PMID 18205950, 2008). "Whereas cytosolic staining was found to be strongly present in a breast cancer case, no staining was detected in sections from the same sample when the section was subject to immunohistochemical analysis using the antibody against derlin-1 that was pre-incubated with peptide antigen." (PMID 18205950, 2008). "In contrast to other breast cancer cell lines included in this study, derlin-1 was constitutively expressed at a high level in SKBR-3 cells, but treatment with TG did not induce further derlin-1 expression in this cell line." (PMID 18205950, 2008).
colorectal cancer (9 papers, 2008 to 2025). A primary or metastatic malignant neoplasm that affects the colon or rectum. "For example, MIAT promotes the proliferation and metastasis of colorectal cancer cells via miR-132/Derlin-1 pathway." (PMID 36934152, 2023). "Furthermore, previous studies reported miR-132-3p restrained growth and metastasis of colorectal cancer cells via decreasing Derlin-1 or cAMP responsive element binding protein 5 (CREB5)." (PMID 33685455, 2021). "Its involvements in cancer are emerging too: in melanoma by acting on key master regulators of the signaling pathway; in papillary thyroid cancer by sponging hsa-miR-324-3p and up-regulating LIM and SH3 domain protein 1 (LASP1); in colorectal cancer by regulating the miR-132/Derlin-1 pathway." (PMID 32605220, 2020). "Interestingly, VCP, a partner of derlin-1 in the retrotranslocation complex, was overexpressed in colorectal carcinomas." (PMID 18205950, 2008). "DERL1 and DERL2 5′-end CpG island were unmethylated in all cases, but DERL3 CpG island promoter hypermethylation was found in four colorectal cancer cell lines: HCT-116, HCT-15, COLO-205 and SW48." (PMID 24699711, 2014). "A recent study on colorectal cancer and MIAT showed that MIAT promoted the growth and metastasis of colorectal cancer cells by regulating the Mir-132/Derlin-1 pathway, indicating the ceRNA relationship between MIAT and Mir-132, which proved that MIAT played the role of ceRNA in Mir-132." (PMID 34108986, 2021).
colon cancer (7 papers, 2014 to 2022). "In human breast, lung, and colon cancer, several lines of direct evidence demonstrated a significant association between Derlin-1 up-regulation and tumor grade, as well as between Derlin-1 up-regulation and lymph node metastasis." (PMID 27977784, 2016). "Our previous study showed that Derlin-1 overexpressed in colon cancer and promoted proliferation of colon cancer cells." (PMID 29686537, 2018). "A study using tissue microarray showed that Derlin-1 was up-regulated in six types of human carcinomas, and Derlin-1-targeting antibodies suppressed colon tumor growth in isogenic mice." (PMID 28178653, 2017). "In human breast, lung, and colon cancers, elevated expression of Derlin-1 was observed, and was found tobe related to tumor grade and lymph node metastasis." (PMID 27977784, 2016). "A study using TMA showed that Derlin-1 is upregulated in six types of human carcinomas, and Derlin-1-targeting antibodies suppress colon tumour growth in isogenic mice." (PMID 24944523, 2014). "Derlin-1 is also overexpressed in bladder and colon cancers." (PMID 28903408, 2017). "Antibodies targeting Derlin-1 suppressed colon tumor growth in isogenic mice." (PMID 27977784, 2016). "Different with our study, Derlin-1 may involve regulation of the PI3K/AKT pathway and contribute to cell proliferation in both colon cancer and hepatocellular carcinoma." (PMID 35205628, 2022).
glioma (7 papers, 2017 to 2023). A benign or malignant brain and spinal cord tumor that arises from glial cells (astrocytes, oligodendrocytes, ependymal cells). "Immunohistochemistry (IHC) results showed that Derlin-1 protein was located in cytoplasm and was positively correlated with the progression of glioma pathological grades." (PMID 28219405, 2017). "Immunohistochemical and western blot were used to determine the expression of HNF1β and Derlin-1 in glioma tissues and cells." (PMID 28219405, 2017). "In the present study, we investigated the expression and functions of circ-TTBK2, miR-217, HNF1β, and Derlin-1 in glioma tissues and cells." (PMID 28219405, 2017). "Further, we found an enhanced expression of Derlin-1 that stimulated glioma cell malignant behaviors." (PMID 28219405, 2017). "Consistent with previously reported, our results demonstrated that Derlin-1 was located in the cytoplasm and had a high expression in glioma tissues and cells." (PMID 28219405, 2017). "Although the oncogenic role of Derlin-1 is confirmed in many tumors, whether Derlin-1 exerts oncogene function in glioma remains unclear." (PMID 28219405, 2017). "More importantly, inhibition of circ-TTBK2/miR-217/HNF1β/Derlin-1 axis may be a potential therapeutic target for human gliomas." (PMID 28219405, 2017). "Since Derlin-1 could be upregulated by HNF1β, we first examined the expression and function of Derlin-1 in glioma tissues and cells." (PMID 28219405, 2017). "In addition, Derlin-1, identified as an oncogene in glioma tissues and cells, was involved in the HNF1β-mediated promotion of glioma cells malignant progression." (PMID 28219405, 2017). "Overexpression of Derlin-1 facilitated malignancy of glioma cells." (PMID 28219405, 2017). "Further, effects of Derlin-1 on glioma cell biological behavior were determined." (PMID 28219405, 2017). "Moreover, Derlin-1 expression levels were obviously higher in low- and high-grade glioma tissues than in normal brain tissues." (PMID 28219405, 2017). "Moreover, HNF1β was a direct target of miR-217 and activated Derlin-1 via binding to its promoter via PI3K/AKT and ERK signaling pathways, suggesting blockage of circ-TTBK2/miR-217/HNF1β/Derlin-1 axis may be a potential therapeutic target for human gliomas." (PMID 32061256, 2020). "Circ-TTBK2 regulated the miR-217/HNF1b/Derlin-1 pathway to promote the progression of glioma; and circ-SHKBP1 regulated the angiogenesis of U87 glioma-exposed endothelial cells through miR-544a/FOXP1 and miR-379/FOXP2 pathways." (PMID 31179240, 2019). "Given that Derlin-1 could be activated by HNF1β, and miR-217 modulated glioma cell progression via targeting 3′-UTR of HNF1β, we next sought to investigate whether Derlin-1 and the downstream pathways were involved in miR-217-induced blunting effect on glioma cells." (PMID 28219405, 2017). "Then, our results demonstrated that Derlin-1, p-PI3K, p-AKT, p-ERK, and p-MEK1/2 were distinctly restored when glioma cells were co-transfected with miR-217 and HNF1β (without 3′-UTR)." (PMID 28219405, 2017).